EPO (erythropoietin)
Diseases named in the same sentence as EPO in open-access papers (continued):
Sharing a sentence is not in itself a finding about the gene and the disease.
lymphoma (8 papers, 2008 to 2025). A malignant (clonal) proliferation of B- lymphocytes or T- lymphocytes which involves the lymph nodes, bone marrow and/or extranodal sites. "An adequate increase of EPO levels was observed in anemic lymphoma patients and notably associated with higher ferritin levels and improvement of Hb (p<0.001)." (PMID 21713081, 2011). "During lymphoma polychemotherapy, 2 out of the 6 patients required EPO and 3 out of the 6 patients required GCSF." (PMID 27749916, 2016). "Our analysis showed that serum EPO levels were higher in lymphoma patients compared with the healthy control group." (PMID 21713081, 2011). "There are few data available regarding the erythropoietin (EPO) levels in conjunction with ferritin in lymphoma patients." (PMID 21713081, 2011). "The observed versus predicted EPO ratio showed also significantly higher levels in anemic lymphoma patients compared to healthy controls (p=0.03)." (PMID 21713081, 2011). "We observed that lymphoma patients had higher EPO levels compared with the healthy control group." (PMID 21713081, 2011). "Furthermore, serum EPO and ferritin levels were higher in lymphoma patients compared with the healthy controls (P=0.001)." (PMID 21713081, 2011). "However, the observed/predicted EPO ratio after adjustment for endogenous EPO response from the normal EPO production/activity continue to demonstrate significantly higher levels in anemic lymphoma patients versus healthy controls (p=0.03)." (PMID 21713081, 2011). "EPO, LDH and ferritin concentrations were similar for newly-diagnosed lymphoma patients and patients who underwent chemotherapy." (PMID 21713081, 2011). "Therefore, the ferritin level may indicate the increase of EPO activity among lymphoma patients." (PMID 21713081, 2011). "EPO, Hb and ferritin levels were significantly higher in non-anemic lymphoma patients compared to healthy controls." (PMID 21713081, 2011). "Furthermore, anemic lymphoma patients (74.4%) had higher EPO levels compared to non-anemic lymphoma patients." (PMID 21713081, 2011). "This may indicate that recombinant human EPO (rhuEPO) treatment is not required in anemic lymphoma patients who have acceptable EPO and ferritin response." (PMID 21713081, 2011).
spinal cord injury (8 papers, 2011 to 2025). Penetrating and non-penetrating injuries to the spinal cord resulting from traumatic external forces (e.g., WOUNDS, GUNSHOT; WHIPLASH INJURIES; etc.). "A single preoperative intraperitoneal administration of a high dose of erythropoietin is safe and effective for neuroprotective actions in patients with traumatic spinal cord injuries." (PMID 40177652, 2025). "Erythropoietin appears to promote functional recovery after spinal cord injury (SCI)." (PMID 35203690, 2022). "Previous studies have shown that the acute administration of recombinant human erythropoietin (rhEPO) in a rat model of spinal cord injury (SCI) reduces lesion size, attenuates gliosis and microglia/macrophage activation as well as enhance myelinogenesis and improve locomotor outcome." (PMID 28840056, 2017).
subarachnoid hemorrhage (8 papers, 2009 to 2024). A serious neurological disorder characterized by intracranial hemorrhage into the subarachnoid space. "In addition, the therapeutic effect of recombinant human erythropoietin (rhEPO) on the subsequent vasospasm after subarachnoid hemorrhage may relate to its inhibition of endothelial apoptosis in cerebral arteries, which may be mediated in part by the JAK2/STAT3 signaling pathway." (PMID 23483946, 2013).
viral infection (8 papers, 2013 to 2025). "First identified in a cancer cell line called erythropoietin-producing hepatocellular, numerous Eph receptors were subsequently detected, exhibiting diverse functions in vascular development, cancer and virus infection." (PMID 25906164, 2015). "We concurrently evaluated the expression of the viral infection- and interferon-stimulated gene ISG56 and the immune-modulatory, hypoxia-regulated gene EPO." (PMID 34185793, 2021). "In parallel, the expression of other anti-viral host cell response related genes, specifically the viral infection- and interferon-inducible gene ISG56 and the immune-modulatory, hypoxia-regulated gene EPO was also analyzed." (PMID 34185793, 2021). "Before and after stimulation with EPO, the cells were analyzed for MS2-VP1u internalization, B19V uptake, and viral infection." (PMID 27690083, 2016). "One day after viral infection, the cells were transferred to a new culture on OP9 cells in the presence of SCF, EPO and dexamethasone (DEX) for 3 days." (PMID 23533656, 2013). "One day after viral infection, the cells were cultured with SCF, EPO and DEX for 4 days." (PMID 23533656, 2013).
acute myeloid leukemia (7 papers, 2010 to 2024). Acute myeloid leukemia (AML) is a group of neoplasms arising from precursor cells committed to the myeloid cell-line differentiation. "One patient that responded to erythropoietin treatment 40,000 U/week, out of 24 (4%), progressed to acute myeloid leukemia, seven years after MDS diagnosis." (PMID 35329991, 2022). "The top down-regulated canonical pathways in which under-represented proteins were detected were putative molecular mechanisms of cancer, acute myeloid leukemia signaling, erythropoietin signaling, mechanisms of viral exit from host cells and IL-3 signaling." (PMID 26538867, 2015). "ANK1 participates in the malignant progression of acute myeloid leukemia in the elderly and in children with Down syndrome, related to erythropoietin, which provides a potential molecular link for MM secondary acute myeloid leukemia and mediating poor prognosis." (PMID 36131282, 2022). "We genotyped the EPO rS1617640 SNP in 189 patients with MDS, 257 with acute myeloid leukemia (AML), 106 with acute lymphoblastic leukemia, 97 with chronic lymphocytic leukemia, 353 with chronic myeloid leukemia, and 95 healthy controls." (PMID 21078205, 2010).
amyotrophic lateral sclerosis (7 papers, 2009 to 2026). Amyotrophic lateral sclerosis (ALS) is a neurodegenerative disease characterized by progressive muscular paralysis reflecting degeneration of motor neurons in the primary motor cortex, corticospinal tracts, brainstem and spinal cord. "In contrast, EPO levels decrease with aging and are further reduced in neurodegenerative diseases, including amyotrophic lateral sclerosis (ALS)." (PMID 41602576, 2026). "In some models of amyotrophic lateral sclerosis, EPO may preserve motor neurons, reduce inflammation, and prevent aggregation of mutant copper/zinc-binding superoxide dismutase, but EPO in amyotrophic lateral sclerosis models may not prolong life span." (PMID 23109841, 2012).
brain edema (7 papers, 2012 to 2024). Increased intracellular or extracellular fluid in brain tissue. "A subsequent subgroup analysis revealed that the combination of EPO with intravenous injections of recombinant tissue plasminogen activator (rtPA) caused complications such as bleedings and brain edema, whereas EPO administration on its own was protective." (PMID 34628598, 2022). "In addition, EPO clearly inhibited local inflammatory reactions and reduced the local inflammatory vasoactive substances and cytotoxic factors that are potentially involved in the inhibition of brain edema." (PMID 23226759, 2012). "Erythropoietin (EPO) has neuroprotective effects in multiple central nervous system (CNS) injury models; however EPO's effects on traumatic brain edema are elusive." (PMID 29179621, 2018). "Infarct size-independent parameters could not demonstrate a statistically significant reduction in cerebral edema with EPO treatment." (PMID 33312715, 2020).
cerebrovascular diseases (7 papers, 2012 to 2025). "For patients with high ERIs, drugs other than EPO can be used to increase the hemoglobin level of MHD patients and prevent the occurrence of cardiovascular and cerebrovascular diseases caused by the side effects of high-dose EPO application." (PMID 41244199, 2025). "Erythropoietin (EPO) is a pleiotropic cytokine reported to prevent neuronal apoptosis in many cerebrovascular diseases." (PMID 36296682, 2022). "These side effects seem to be primarily due to the erythropoietic mode of action of the EPO derivate, and it is conceivable in principle that they limit the extent of neuroprotection in the context of acute cerebrovascular diseases." (PMID 33312715, 2020).
chorioamnionitis (7 papers, 2018 to 2023). A morphologic finding indicating inflammation of the fetal sac membranes. "In addition, in a rat model of preterm birth following dual intrauterine injuries from placental malperfusion and chorioamnionitis on E18, melatonin, in combination with erythropoietin (EPO), dampened molecular, sensorimotor, cognitive, and social abnormalities in adult rats." (PMID 37627625, 2023). "Specifically, we predicted that EPO, EPOR, MLTR1, SIRT1, HIF1α and HIF2α alterations after chorioamnionitis (CHORIO) would reflect relative changes observed in human preterm infants." (PMID 37546540, 2023). "Additionally, antenatal factors did not correlate with brain injury markers (hypothesis I), but multiple pregnancy, prenatal steroid administration and chorioamnionitis had moderate impact on EPO and SDF-1 levels (hypothesis K) and more intense impact on levels of CPCs (hypothesis L)." (PMID 37292373, 2023). "Indeed, both EPO and MLT are known to affect Th1/Th2 ratio, Th17, neutrophils, and microglia, major cellular mediators of chorioamnionitis and PBI." (PMID 29706928, 2018).
chronic hepatitis C (7 papers, 2009 to 2023). "Here, we examined for the first time a single nucleotide polymorphism (SNP) within the EPO gene promoter, rs1617640, in chronic hepatitis C patients who were undergoing antiviral treatment." (PMID 25227310, 2014). "In a study by Amanzada and coworkers among chronic hepatitis C patientsundergoing antiviral treatment, individuals with the EPO rs1617640 CCgenotype had a weaker rise of erythropoietin levels and a higher likelihood ofneeding blood transfusions." (PMID 39077006, 2023). "Another study could also show that the median EPO serum level increased at week 12 to 41 mIU/ml (range 12–683 mIU/ml) in 145 patients with chronic hepatitis C during PEG-IFN-α and RBV therapy." (PMID 25227310, 2014). "There are also several cases in the literature of patients with chronic hepatitis C who developed PRCA but did not receive recombinant erythropoietin." (PMID 26240773, 2015).
colitis (7 papers, 2011 to 2023). Inflammation of the colon. "The observed clinical and histopathological improvement of colitis upon EPO or cibinetide treatment was also associated with reduced levels of nitrite, TNF, IL-1ß, IL-6, IL-12p70, IL-23, IFN-γ and IL-17A in supernatants of colonic organ cultures." (PMID 29026145, 2017). "TNBS-colitis causes a substantial decrease in colonic EPO mRNA levels whereas splenic EPOR expression is significantly down-regulated in response to systemic Salmonella infection." (PMID 22094132, 2012). "The treatment with cEPO at 500 and 1000 IU/kg significantly reduced the concentration of creatinine (p < 0.01 and p < 0.05, respectively), which is in accordance with the results of our research group in the acute colitis model with EPO." (PMID 37760938, 2023). "Since it was evaluated in an acute model of colitis, and the experiment took four days in total, it would be interesting to evaluate the EPO derivate at the same doses but now in a chronic animal model of IBD, which is the objective of this experiment." (PMID 37760938, 2023). "EPO knockout mice in a dextran sulfate-induced model of ulcerative colitis provide clear evidence of the essential role of EPO in the pathogenesis of colitis." (PMID 30284485, 2018). "We found that both cibinetide and EPO ameliorated the clinical course of experimental colitis in mice, resulting in improved weight gain and survival." (PMID 29026145, 2017). "Once colitis was established, mice were treated with solvent, EPO or the selective IRR agonist cibinetide." (PMID 29026145, 2017). "These anti-inflammatory effects of EPO are in a line with observations in mice showing an ameliorated clinical course of experimental arthritis, colitis and encephalomyelitis following EPO treatment." (PMID 22094132, 2012). "In a recent study in autoimmune model of colitis and the systemic infection with salmonella treatment with EPO concordantly reduced the activation of NF-kappaB and thereby reduced the immune activation." (PMID 22043313, 2011). "Moreover, it has been shown that EPO ameliorates disease activity in experimental arthritis, encephalomyelitis and colitis in mice, suggesting that EPO exerts anti-inflammatory and tissue protective effects in autoimmune diseases." (PMID 29026145, 2017). "In chemically induced colitis, EPO treatment was suggested to inhibit induction of activated macrophages and expression of proinflammatory genes such as inducible NO synthase (iNOS/NOS2), TNF-α, interleukin 6, and blocks NF-κB activation to limit tissue damage in the gut." (PMID 24918289, 2014). "EPO thus exerts anti-inflammatory effects by inhibiting NF-κB-dependent immune-driven cytokine production which ameliorates the clinical course of experimental colitis while this has been shown to be detrimental in systemic infection with viable Salmonella." (PMID 22094132, 2012). "Full length EPO has anti-inflammatory effects in a model of inflammatory bowel disease, namely DSS-colitis, that are mediated via NF-κB de-activation." (PMID 29026145, 2017). "Furthermore, in the acute model of colitis, TNF-⍺ concentrations were higher in the TNBS group compared to the EPO-treated groups, proving its pro-inflammatory effect." (PMID 37760938, 2023). "While EPOR expression in the colon is not affected by chemically induced colitis, colonic inflammation results in a significant reduction of local EPO mRNA production." (PMID 22094132, 2012).
dementia (7 papers, 2019 to 2025). Loss of intellectual abilities interfering with an individual's social and occupational functions. "Our total population-based retrospective cohort study revealed that long-term administration of EPO to HD patients was inversely associated with their general risk of developing dementia as well as specific dementia subtypes, including VaD and UnD." (PMID 31484803, 2019). "Nonetheless, our study demonstrated a 47% risk reduction for developing dementia in HD patients who used EPO supplementation in the range of 71-200 annual DDDs." (PMID 31484803, 2019). "The risk of incident dementia in relation to the combination of EPO and iron use was evaluated in HD patients, as compared with those who used neither drug." (PMID 31484803, 2019). "Analyzing the annual DDDs of EPO indicated that the low-, medium- and high-dose groups exhibited reduced dementia rates compared with the non-EPO cohort, suggesting a reduction of risk for annual various DDDs of EPO <200." (PMID 31484803, 2019). "The risk of incurable dementia (UnD) and vascular dementia (VaD) was also lower in the EPO group." (PMID 35206577, 2022). "We estimated whether EPO supplementation correlated with reductions in risk for specific dementia subtypes based on the tertile of annual DDDs for EPO use." (PMID 31484803, 2019). "Patients who exhibited higher annual DDDs of EPO exhibited a decreased risk of dementia (28%–47%)." (PMID 31484803, 2019). "The risk of dementia was further reduced in HD patients treated with EPO in combination with iron." (PMID 31484803, 2019). "The novel circadian clock gene pathways that involve autophagy, mTOR, and (SIRT1) and include FoxOs and EPO offer exciting prospects for the development of new strategies to understand cognitive loss and to overcome challenges that can limit the onset and progression of dementia." (PMID 34356626, 2021). "Therefore, we conducted a total population-based retrospective cohort study to test whether EPO and intravenous iron supplementation correlate with the risk of various dementia subtypes including AD, VaD, and unspecified dementia (UnD) in HD patients." (PMID 31484803, 2019). "The data concerning the effects of EPO and intravenous iron supplementation on specific dementia subtypes among HD patients are scarce." (PMID 31484803, 2019). "In comparison with non-EPO patients, HD patients treated with EPO were less likely to experience some subtypes of dementia during the follow-up period after the index healthcare use." (PMID 31484803, 2019). "Incidence, hazard ratios and interaction (between EPO and intravenous iron) for dementia among hemodialysis cohort treated with EPO or intravenous iron." (PMID 31484803, 2019). "Incidence, hazard ratios and interaction (between EPO and intravenous iron) for dementia subtypes among hemodialysis cohort treated with EPO or intravenous iron." (PMID 31484803, 2019). "Upon dementia diagnosis, the cumulative EPO dosage was recorded as the total of annual DDDs from drug initiation to the day before the diagnosis." (PMID 31484803, 2019). "Patients receiving EPO had a 39% lower risk of general dementia than those in the non-EPO group.The risk of dementia was further reduced in HD patients with EPO treatment in combination with iron." (PMID 35206577, 2022). "Stratified Cox proportional hazard regressions showed that the hazard ratio (HR) for dementia in HD patients who took EPO within the follow-up period was 0.48 [95% confidence interval (CI) 0.42 to 0.54; p<0.0001] in comparison with the HD patients in the non-EPO cohort." (PMID 31484803, 2019). "Using hazard ratios and Cox regression models, we found that patients receiving EPO had a 39% lower risk of general dementia than those in the non-EPO group." (PMID 31484803, 2019). "Moreover, our results suggest that intravenous iron supplementation correlates with lower risks of dementia in HD patients, especially in combination with EPO." (PMID 31484803, 2019).
dementia (continued). "In addition, HD patients using EPO and iron treatments experienced a delayed onset of dementia or prevented it altogether (log-rank test, p < 0.0001)." (PMID 31484803, 2019). "Here, after controlling for potential confounders, we found that EPO use of less than 71 annual DDDs, 71–200 annual DDDs, and over 201 annual DDDs in cumulative dose is associated with a 28%, 47%, and 38% risk reduction in dementia, respectively, as compared with not using EPO." (PMID 31484803, 2019). "Our study was restricted to analyzing data for HD patients, who already suffer from a high risk of developing dementia; therefore, our results may not be applicable to non-HD patients and further research is need to characterize the effects of EPO supplementation among the general population." (PMID 31484803, 2019).
glomerulonephritis (7 papers, 2008 to 2024). A renal disorder characterized by damage in the glomeruli. "Additional study of the PD-1 axis in glomerulonephritis may offer insight into the formation of germinal centers, fibrosis, and changes in erythropoietin production in the disease." (PMID 33676416, 2021). "Glomerulonephritis as a primary renal diagnosis influenced EPO towards a higher dose (p = 0.008), but not Hb." (PMID 19077225, 2008). "Unlike glomerulonephritis, erythropoietin production may be elevated in RCC and B cells are not commonly detected in RCC." (PMID 33676416, 2021). "Glomerulonephritis influenced EPO to a higher dose, but not Hb." (PMID 19077225, 2008). "Independent occurrence of peritubular capillaritis together with tubulointerstitial inflammation without glomerulonephritis was described in some case reports, which furthermore points out that vascular injury impairs the tubulointerstitial compartment, hence it might affect EPO-producing cells." (PMID 37676636, 2023).